USP17L24 (ubiquitin specific peptidase 17 like family member 24)
Description:
Deubiquitinating enzyme that removes conjugated ubiquitin from specific proteins to regulate different cellular processes that may include cell proliferation, progression through the cell cycle, apoptosis, cell migration, and the cellular response to viral infection.
Target class: Enzyme; Hydrolase
Gene: Protein-coding gene on chromosome 4 (9,325,165 to 9,326,757, forward strand). Ensembl gene ENSG00000232264.
Subcellular location: Nucleus, nucleolus; Endoplasmic reticulum
Pathways (Reactome):
Metabolism of proteins: Ub-specific processing proteases
Gene Ontology:
Molecular function: cysteine-type deubiquitinase activity; hyaluronic acid binding; RNA binding
Biological process: positive regulation of epithelial cell apoptotic process; protein deubiquitination involved in ubiquitin-dependent protein catabolic process; regulation of apoptotic process; protein deubiquitination
Cellular component: nucleolus; nucleus; endoplasmic reticulum
Homologues: Paralogues in human: USP17L25 (100% identical), USP17L26 (100% identical), USP17L27 (100% identical), USP17L28 (100% identical), USP17L29 (100% identical), USP17L30 (100% identical), USP17L5 (99% identical), USP17L20 (99% identical), USP17L11 (99% identical), USP17L17 (99% identical), USP17L18 (99% identical), USP17L22 (99% identical), and 59 more.
Diseases named in the same sentence as USP17L24 in open-access papers:
USP17L24 is named in the same sentence as 1 disease in open-access papers, as found by Europe PMC text mining. Sharing a sentence is not in itself a finding about the gene and the disease.
USP17L24 shares sentences with these, for which no sentence is quoted: lymphoma (1 paper).